GSK3B (glycogen synthase kinase 3 beta)
Diseases named in the same sentence as GSK3B in open-access papers (continued):
Sharing a sentence is not in itself a finding about the gene and the disease.
pancreatic cancer (continued). "The inhibition of GSK‐3β results in the suppression of pancreatic tumor growth and survival of pancreatic cancer cells related to NF‐κB." (PMID 39632551, 2024). "Because SFN inhibited growth and induced apoptosis in Mia PaCa‐2 cells, the effect of SFN on the phosphorylation of GSK‐3β, which plays a significant role in pancreatic cancer progression, was tested." (PMID 39632551, 2024). "GSK‐3β is a key regulator of NF‐κB in pancreatic cancer cells, which controls the expressions of genes governing cell proliferation, apoptosis, inflammation, angiogenesis, infiltration, and drug resistance." (PMID 39632551, 2024). "For instance, an inhibitor of GSK3B has been found to decrease pancreatic cancer growth and metastasis in mice." (PMID 38814517, 2024). "Previous reviews have described the roles of GSK3β in mediating Notch and mTOR signaling in different cancer types, including pancreatic cancer." (PMID 38318525, 2024). "Glycogen synthase kinase‐3 beta (GSK‐3β), a serine/threonine kinase, plays a significant role in pancreatic cancer progression, influencing tumor growth, metastasis, and treatment resistance." (PMID 39632551, 2024). "Overall, GSK3β has characteristics of a promising therapeutic target to overcome chemoresistance in pancreatic cancer." (PMID 38318525, 2024). "GSK‐3β inhibition decreases the expression of NF‐κB and NF‐κB‐mediated expression of cMyc in pancreatic cancer, thereby reducing tumor growth." (PMID 39632551, 2024). "For instance, higher expression of GSK-3β is observed in colon, liver, ovarian, and pancreatic cancers whereas overexpression of GSK-3β promotes hyperphorphorylation of Tau in AD." (PMID 36829686, 2023). "We have previously demonstrated that GSK-3β gene expression is a target of oncogenic KRas signaling in pancreatic cancer cell lines and pancreas-specific deletion of GSK-3β in KRasG12D mice reduces cearulein-induced ADM and PanIN lesion development." (PMID 35646902, 2022). "In summary, our study demonstrated that COL11A1 effectively induced EMT progression and cell stemness by activating the AKT/GSK-3β/Snail signaling pathway to enhance the migration and invasion abilities of pancreatic cancer cells." (PMID 35327583, 2022). "Transcriptomic sub-types of pancreatic cancer were found to acquire sensitivity or tolerance to GSK-3β inhibitors." (PMID 36430630, 2022). "Increased GSK-3β activity is observed in cancer cells, as well as in metastatic lesions, and is responsible for the inherent chemoresistance observed in pancreatic cancer." (PMID 36430630, 2022). "The prognostic risk score model contained three genes: GSK3B, IL18 and VEGFA, all of which were highly expressed in pancreatic cancer tissue and were associated with poor prognosis." (PMID 36743929, 2022). "Akt/GSK3β phosphorylation and c-Myc and Cyclin D1 expression were assessed in pancreatic cancer cells." (PMID 35422475, 2022). "Overexpression of GSK-3β has been observed in various tumour types, including colon, liver, ovarian, and pancreatic cancers." (PMID 36430630, 2022). "GSK-3β nuclear accumulation was found to significantly correlate with human pancreatic cancer de-differentiation and regulation of NF-κB." (PMID 36430630, 2022). "In pancreatic cancer, GSK-3β is involved in regulating cancer cell proliferation, resistance to apoptosis and autophagy, chemo-resistance, and EMT, leading to invasion and metastasis." (PMID 36430630, 2022). "We applied Cox and LASSO regression analysis to develop a neuroendocrine regulation- and metabolism-related prognostic risk score model with three genes (GSK3B, IL18 and VEGFA) for pancreatic cancer." (PMID 36743929, 2022). "In this study, we generated a new mouse model to investigate the contribution of nuclear GSK-3β to KRasG12D-driven pancreatic cancer development." (PMID 35646902, 2022).
pancreatic cancer (continued). "In the present study, we elucidated the function of COL11A1 in promoting EMT and cell stemness via the AKT/GSK-3β/Snail signaling pathway, which facilitates the invasion and migration of pancreatic cancer cells." (PMID 35327583, 2022). "First, GSK-3β is a downstream target of the pancreatic cancer initiating and promoting K-ras pathway." (PMID 36430630, 2022). "In pancreatic cancer, knockdown of GSK-3β leads to a decrease in Bcl-2 and VEGF levels, thereby inhibiting tumor growth and angiogenesis." (PMID 34719320, 2022). "This Hh-GLI impairment has also been demonstrated in preclinical models by a combination of the GSK-3β inhibitor lithium and gemcitabine dosing in pancreatic cancer." (PMID 36430630, 2022). "Taken together, these data suggest that expression of GSK-3β and KRasG12D result in a transcriptional switch from pancreatic acinar cells to ductal cells, with expression of pancreatic tumor precursor markers." (PMID 35646902, 2022). "GSK-3β is demonstrated to be a critically important kinase for the survival and proliferation of K-Ras–dependent pancreatic cancer cells." (PMID 34955846, 2021). "The reduction in PD-1 levels, enhancement of cytotoxic T cell activity via GSK-3β inhibition has been seen in the context of various syngeneic mouse models including pancreatic cancer models." (PMID 34356465, 2021). "High expression levels of GSK3B and robust basal autophagy flux in the pancreatic cancer cell lines BxPC3, MIA PaCa-2, and CFPAC were previously reported." (PMID 33654220, 2021). "GSK-3β inhibition in pancreatic cancer cells leads to perturbations in Rac1 and F-actin subcellular localization, reduced production of MMP-2, and decreased phosphorylation of FAK, leading to inhibition of cell migration and invasion." (PMID 34356465, 2021). "GSK-3β is mainly considered to be a cytoplasmic protein but is found to be aberrantly accumulated in the nucleus in pancreatic cancer cell lines and human pancreatic adenocarcinomas." (PMID 34955846, 2021). "This phosphorylation status of ULK1 is well correlated with the high expression levels of GSK3B in pancreatic cancer cell lines, compared with HPNE cells." (PMID 33654220, 2021). "On the other hand, GSK3β inhibition in pancreatic cancer cells suppresses Rb phosphorylation by cyclin D/cyclin-dependent kinase 4 or 6 complex and its subsequent degradation." (PMID 32767962, 2021). "Later, it was demonstrated that activation of the Ras–MAPK–ETS2–p300 cascade leads to GSK-3β overexpression in pancreatic cancer cells." (PMID 34955846, 2021). "Future studies should aim to study new combination treatments involving glycogen synthase kinase-3 beta targeting drugs with chemotherapy and immunotherapy in pancreatic cancer." (PMID 34356465, 2021). "GSK3β also seems to be responsible for NFkB aberrant activity in pediatric acute lymphoblastic leukemia and pancreatic cancer cells." (PMID 32767962, 2021). "Similar effects have been observed after GSK3β inhibition by AR-A01441 in human pancreatic cancer cell lines: MIA PaCa-2 and PANC-1." (PMID 34440861, 2021). "Inhibition of GSK-3β has the potential to reinvigorate exhausted cytotoxic T cells in the immune suppressive tumor microenvironment of pancreatic tumors." (PMID 34356465, 2021). "In our previous study, FHL3 also acts as a regulator in ubiquitin degradation process of EMT-TFs through Akt/GSK3β/ubiquitin pathway in pancreatic cancer." (PMID 34150617, 2021). "Our previous study has revealed Four and a Half LIM Domains 3 (FHL3) plays as a binding partner of Glycogen Synthase Kinase 3 Beta (GSK3β), promoted tumor metastasis in pancreatic cancer." (PMID 34150617, 2021). "Apigenin has also been shown to induce G2/M cell cycle arrest and apoptosis in BxPC-3 and PANC-1 pancreatic cancer cell lines via targeting GSK3β/NF-kB signaling cascade." (PMID 32717779, 2020).
pancreatic cancer (continued). "Similar results were observed with other flavonoids such as quercetin and luteolin, indicating their potential in targeting GSK3β signaling to suppress pancreatic cancer." (PMID 32717779, 2020). "It has been reported that inhibition of GSK3β in pancreatic cancer and NSCLC stabilizes β-catenin and thereby induces tumor cell death via transactivation of pro-apoptotic c-Myc." (PMID 32503133, 2020). "Consistently, GSK3B inhibition has been shown to increase autophagy flux in mice liver and human pancreatic cancer cells." (PMID 32511341, 2020). "Subsequently, we demonstrated that pharmacological GSK3β-specific inhibitors reduced the migration and invasion of pancreatic cancer cells and glioblastoma cells, both of which are highly invasive tumor types." (PMID 32503133, 2020). "Paradoxically, the induction of Wnt/β-catenin signaling through inhibition of GSK3β has been shown to suppress tumor cell survival and proliferation in osteosarcoma and rhabdomyosarcoma, pancreatic cancer and non-small cell lung cancer (NSCLC)." (PMID 32503133, 2020). "Meanwhile, a study has demonstrated that silencing galectin-3 can inhibit the migration and invasion of pancreatic cancer cells by down-regulating the level of Akt phosphorylation and GSK-3β protein." (PMID 30996686, 2019). "MiR-137-mimic significantly promoted AXIN1 and APC, GSK-3β, the phosphorylation of β-catenin on Ser45 expression, and reduced the β-catenin of cytoplasm and nuclear expression in pancreatic cancer cells." (PMID 30866999, 2019). "Another study has also demonstrated thathigh expression of miR-940 promotes proliferation of pancreatic cancer throughregulating GSK3β and sFRP1." (PMID 31085718, 2019). "p21-activated kinase 3 (PAK3) controls Akt-GSK3β (Glycogen Synthase Kinase 3 beta)-β-catenin signaling in pancreatic cancer cells." (PMID 31416295, 2019). "A study in pancreatic cancer cells has shown that GSK-3β inhibition leads to nuclear translocation of TFEB47." (PMID 29445085, 2018). "In the current study, we first demonstrated in pancreatic cancer cells that inhibition of PP2A contributed to the regulation of GSK‐3β through dephosphorylation of GSK‐3β." (PMID 29863120, 2018). "Clinical application of this study was to identify the level of GSK‐3β or PP2A in a biopsy sample or in an endoscopic ultrasound‐guided fine‐needle aspiration sample before giving FUT‐175 to patients with pancreatic cancer." (PMID 29863120, 2018). "Further, we found that key nodes of regulation by our confirmed hits in this interaction map were known molecules that modulate survival, EMT and drug resistance in Ras mutated pancreatic cancers, such as YAP1, SIRT1, BAG3, ILK, CDK5, HDACs or GSK3β." (PMID 30325918, 2018). "Levels of cleaved caspase‐8 of both pancreatic cancer cell lines were increased in line with the presence of phosphorylated GSK‐3β." (PMID 29863120, 2018). "On the other hand, induction of apoptosis in pancreatic cancer cells was observed after application of GSK-3β (CHIR-99021) kinase inhibitor." (PMID 29214525, 2017). "In contrary, aberrant expression of GSK3β has been seen in various types of cancer such as liver, colon, ovarian, and pancreatic cancers." (PMID 26968952, 2016). "GSK-3β served as a tumor activator in pancreatic cancer, and phosphorylation at Ser 9 reduced the activity of this kinase." (PMID 27705937, 2016). "We previously reported that GSK-3β inhibition sensitizes pancreatic cancer and glioblastoma cells to gemcitabine and temozolomide, respectively, as well as sensitizing them to ionizing radiation through the modulation of distinct molecular pathways." (PMID 27780915, 2016). "Plexin A1 activation via SEMA3 treatment in different pancreas cancer cell lines has been previously shown to activate Rac1, GSK3β and p44/p42 MAPK signaling." (PMID 26962861, 2016).
pancreatic cancer (continued). "This notion is supported by recent studies suggesting an involvement of GSK3β in pancreatic cancer cell survival, dedifferentiation as well as therapeutic resistance." (PMID 27602497, 2016). "Further, we show that activation of the WNT pathway stabilizes intracellular CD24 protein in pancreatic tumor cells, and that inhibition of GSK3β has the same effect, while transcriptional activation of β-catenin is not required in this process." (PMID 27203385, 2016). "In colon and pancreatic cancer cells, NF-κB is positively regulated by GSK3β and its activation confers a selective growth advantage on these cells, so acting as a tumor promoter." (PMID 25738332, 2015). "In colon and pancreatic cancer cells, GSK3β activates a proliferative signal by activation of NF-κB, and inactivation of GSK3β inhibits NF-κB activity." (PMID 25738332, 2015). "To investigate the molecular mechanism of GSK3β in pancreatic cancer tissues, we created stable PANC1 cells up-regulation of GSK3β by transfecting GSK3β overexpression plasmid, and down-regulation of GSK3β using two different types of RNA interference." (PMID 26213494, 2015). "MiR-33a inhibited the Pim-3 kinase-mediated AKT/Gsk-3β/β-catenin pathway in pancreatic cancer cells." (PMID 25971209, 2015). "Further, our findings provide new information on possible mechanisms of action for RV and AC in pancreatic cancer cells which involve regulation of the subcellular localization of GSK3β and ERK1/2." (PMID 26556864, 2015). "In spite of this evidence, the precise role of GSK3β and its potential as a therapeutic target in pancreatic cancer still require further research." (PMID 26213494, 2015). "Several reports showed that GSK3β is overexpressed in various tumor types including pancreatic cancer." (PMID 26556864, 2015). "This study provides further insight into the molecular mechanism of GSK3β-induced pancreatic cancer invasion, and will allow exploration of novel therapeutic strategies for pancreatic cancer that target GSK3β and/or CXCR4/MMP-2." (PMID 26213494, 2015). "In this study, we demonstrated that GSK3β induced PANC1 pancreatic cancer cell invasion via the CXCR4/MMP-2 pathway." (PMID 26213494, 2015). "Recent studies have also indicated that GSK3β promotes the proliferation and invasion of pancreatic cancer cells." (PMID 26213494, 2015). "Glycogen synthase kinase-3β (GSK3β) expression and activity are upregulated in pancreatic cancer tissues." (PMID 26213494, 2015). "Inhibition of GSK3β also suppressed pancreatic cancer growth and angiogenesis by decreasing the expression of Blc-2 and vascular endothelial growth factor (VEGF), and abrogating NFκB activity." (PMID 26213494, 2015). "Among the current range of novel target molecules, GSK3β has emerged as a therapeutic target in pancreatic cancer." (PMID 26213494, 2015). "A recent study has indicated that mutant K-ras-mediated signaling increases GSK3β expression in pancreatic cancer cells by the MAPK signaling pathway." (PMID 26556864, 2015). "Inhibition of GSK3β triggered an apoptotic response in pancreatic cancer cells via a JNK-dependent mechanism, and attenuated cell survival and proliferation and induced apoptosis in pancreatic cancer cell lines." (PMID 26213494, 2015). "Together, these results indicated that activation of GSK3β is essential for zidovudine-dependent resensitization to gemcitabine-induced cell death in gemcitabine-resistant pancreatic cancer cells." (PMID 26111057, 2015). "For example, GSK3β knockout or lithium treatment potentiates apoptosis in hepatocytes, and an increased rate of apoptosis following the inhibition of GSK3β has been reported in prostate cancer, pancreatic cancer, leukemia, glioma and bladder cancer." (PMID 24618715, 2014). "A redundant role with GSK3B has been described in pancreatic cancer cells where both isoforms are involved in NFkB-dependent pro-survival effect." (PMID 24984063, 2014).
pancreatic cancer (continued). "In contrast, GSK3β was shown to participate in cell survival in pancreatic cancer hence behaving as a tumor promoter." (PMID 25937997, 2014). "In contrast to our result, a recent study reported that siRNA-mediated GSK3β silencing promotes pancreatic cancer cell survival following irradiation via stabilization and activation of β-catenin." (PMID 23408967, 2013). "Immunohistochemistry for the serial sections showed that GSK3β and p-GSK3βY216 were diffusely expressed and colocalized in the tumor cells and overexpressed in the invasive tumor cells of 8/15 (53%) pancreatic cancer patients." (PMID 23408967, 2013). "It was previously reported that anti-GSK3β treatments in other cancer types, including pancreatic cancer and glioblastoma, sensitize the cells to chemotherapeutic reagents and ionizing radiation." (PMID 23941783, 2013). "Here we investigate a pathological role for GSK3β in the invasive and treatment resistant phenotype of pancreatic cancer." (PMID 23408967, 2013). "While the levels of GSK3β activity differ between the pancreatic cancer cells examined in this study, its inhibitor AR-A014418 has the similar IC50 values against them." (PMID 23408967, 2013). "Here we investigated the potential involvement of GSK3β in the invasive nature of pancreatic cancer and its resistance to gemcitabine and ionizing radiation, the two major obstacles to more effective treatment." (PMID 23408967, 2013). "Treatment with 10 μM AR-A014418 reduced the levels of p-FAKY397 and p-FAKY861, suggesting a pivotal role for the GSK3β/FAK/Rac1 pathway in promoting pancreatic cancer cell invasion." (PMID 23408967, 2013). "Here, we found overexpression of GSK3β and its active form in the tumor cells in the invasive primary pancreatic cancers." (PMID 23408967, 2013). "The results provide a biological rationale for combinational treatment strategies that include targeting of GSK3β in order to control refractory pancreatic cancer." (PMID 23408967, 2013). "Pancreatic cancer cells were examined for GSK3β expression, phosphorylation and activity using Western blotting and in vitro kinase assay." (PMID 23408967, 2013). "Based on earlier studies that demonstrated involvement of GSK3β in NF-κB-mediated cell survival, GSK3β was found to support the survival of pancreatic cancer cells via this pathway." (PMID 23408967, 2013). "Pancreatic cancer cells showed higher basal levels of GSK3β and the Y216-phosphorylated active form (p-GSK3βY216) and lower levels of the S9-phosphorylated inactive form (p-GSK3βS9) compared to HEK 293 cells." (PMID 23408967, 2013). "The targeting of GSK3β represents an effective strategy to overcome the dual challenges of invasiveness and treatment resistance in pancreatic cancer." (PMID 23408967, 2013). "GSK3β was reported to sustain pancreatic cancer cell survival by maintaining the transcriptional activity of NF-κB." (PMID 23408967, 2013). "Since UVC failed to affect p44/p42 MAPK and SAPK/JNK by PDGF-BB, it is likely that UVC inhibits PDGF-BB-induced migration by suppressing Akt-GSK-3β pathway in pancreatic cancer cells." (PMID 22200892, 2012). "Our findings indicate that GSK3β inhibition combined with chemotherapy is a novel and promising strategy to sensitize pancreatic cancer cells to gemcitabine." (PMID 24212624, 2011). "GSK3β has also emerged as a mediator of pathological states, including glucose intolerance, inflammation, and various cancers (e.g., pancreatic cancer)." (PMID 24212624, 2011). "Based on the potential involvement of GSK3β in NF-κB-mediated cell survival, a number of studies demonstrated that GSK3β is involved in pancreatic cancer cell survival via the NF-κB pathway." (PMID 24212624, 2011). "GSK3β has emerged as a critical factor that plays distinct pathologic roles in glucose intolerance, inflammation, and in various cancer types (e.g., pancreatic cancer)." (PMID 24212624, 2011).